EGFR (epidermal growth factor receptor)
Diseases named in the same sentence as EGFR in open-access papers (continued):
Sharing a sentence is not in itself a finding about the gene and the disease.
lung cancer (continued). "Many studies have been conducted to find the most accurate method for determining EGFR mutations in the cftDNA of lung cancer patients, including technologies such as ARMS, PNA-clamp, DHPLC, and NGS." (PMID 33297595, 2020). "Drugs targeting specific mutated genes or specific activated pathways are clinically available for several indications, e.g. for EGFR-mutated lung cancer." (PMID 32264863, 2020). "Advances in DNA sequencing technology revealed the driver mutations in lung cancers at the genes including EGFR, ROS1, BRAF, ALK, and KRAS." (PMID 33276627, 2020). "Another study assessed real‐world patterns of epidermal growth factor receptor (EGFR) testing and associated treatment and outcomes among non‐small cell lung cancer (NSCLC) population." (PMID 32638440, 2020). "The frequency of SREs in EGFR mutated lung cancer with bone metastases have been scarcely documented in literature and the benefit of TKIs on bone pain and SREs prevention have not evaluated in randomized clinical trials." (PMID 33282740, 2020). "Since TMB and efficacy of EGFR-Tyrosine kinase inhibitors in patients with EGFR-mutant lung cancers have been investigated and found to be negatively associated in lung cancer patient treated with EGFR TKI." (PMID 32397977, 2020). "In lung cancer treatment, gene sequencing has been performed mainly as a companion diagnostic approach for identifying mutations in genes such as EGFR and anaplastic lymphoma kinase (ALK) and subsequent selection of molecular target drugs." (PMID 33233456, 2020). "Except for the inevitable acquired resistance, EGFR TKIs are more relevant to EGFR-activating mutations than to WT-EGFR, suggesting that this strategy will achieve relatively little benefit in the majority of lung cancer patients who harboring with WT-EGFR." (PMID 32694521, 2020). "Considering the complexity of lung cancer treatments and interactions between treatment strategies, the influence of EGFR mutations on the radiation response has seldom been proven in clinical studies." (PMID 32693792, 2020). "Studies in lung cancer have presented the association between EGFR mutation status and quantitative features extracted from computed tomography (CT) scans." (PMID 32107398, 2020). "Epidermal growth factor receptor tyrosine kinase inhibitors (EGFR-TKIs) are used for treating EGFR-mutated lung cancer, and osimertinib is effective in cases that acquired T790M mutations after treatment with the first- and second-generation EGFR-TKIs." (PMID 32517152, 2020). "Previous studies in lung cancer suggested that KRAS mutation is a poor prognostic marker for response to EGFR TKI treatment." (PMID 32505185, 2020). "Accurate and rapid quantification of EGFR mutation status is critical in identifying of lung cancer patients suitable for EGFR-TKI treatment, and provides a potential possibility for guiding ICI immunotherapy." (PMID 33067442, 2020). "In lung cancer, a rapid decrease in the serum concentration of mutated EGFR-DNA 14 days after initiating treatment with erlotinib (a tyrosine kinase inhibitor) was associated with tumour shrinkage 2 months later." (PMID 32423477, 2020). "The presence of tumor stem cells has been reported in multiple cancers, including lung cancer with EGFR mutation." (PMID 33291316, 2020).
lung cancer (continued). "A previous phase II trial (Okayama Lung Cancer Study Group Trial 1001) showed that gefitinib in combination with bevacizumab as first-line therapy for advanced EGFR-mutated NSCLC resulted in a median PFS of 14.4 months." (PMID 33113888, 2020). "The molecular characterization of lung adenocarcinoma has revolutionized the treatment of lung cancer with the discovery of targetable genetic alterations such as EGFR mutations and ALK gene rearrangements." (PMID 32149365, 2020). "A previous study indicated that afatinib inhibits lung cancer cells with specific EGFR mutations more effectively than other EGFR‐TKIs such as osimertinib." (PMID 32495514, 2020). "One well known example is lung cancer, in which EGFR overexpression was associated with poor prognosis." (PMID 33396916, 2020). "Our study involved several lung cancer models including H1975 (EGFR mutations), A549 (KRAS mutation), and H1299 (NRAS mutation)." (PMID 33214553, 2020). "Of particular interest is the finding that Asian women with the EGFR mutation developed adenocarcinoma at an earlier age than other lung cancer patients." (PMID 32850378, 2020). "Screening for rare lung cancer cells harboring the T790M mutation in the EGFR sequence showed that the T790M-mutated cancer cells had a strong fluorescent signal, which was observed in proportion to the spiking concentrations in the non-mutated cancer cells." (PMID 32605095, 2020). "We found that TAS-116 decreased phosphorylated EGFR levels and inhibited the growth of EGFR-mutated lung cancer cell lines." (PMID 31857719, 2020). "The molecular test of EGFR mutation predicted the response rates of tyrosine kinase inhibitors (TKIs) treatment in the lung cancer patients." (PMID 31935933, 2020). "During in vitro cell proliferation assays, afatinib exhibited a lower half maximal inhibitory concentration (IC50) than other TKIs, including osimertinib, against lung cancer cell lines with minor EGFR mutations." (PMID 32495514, 2020). "It is noteworthy that the EGFR-activating mutations identified in lung cancers have been well demonstrated to predict response to erlotinib." (PMID 32929368, 2020). "Nonsquamous non‐small cell lung cancers (NSCLC) account for approximately 65% of lung cancers in men and 85% of lung cancers in women; 30%–40% of these have mutations in the epidermal growth factor receptor (EGFR) gene in patients in Asia." (PMID 32495514, 2020). "We monitored the proliferation of EGFR mutation lung cancer cell lines H1650, H1975, and HCC827 using a Real-Time Cellular Analyzer (RTCA) under simultaneous treatment with rHuEPO and Afatinib, which we compared to Afatinib treatment alone." (PMID 32922549, 2020). "Previous study showed that the polymorphism of CYP1A1 was associated with the treatment outcome of EGFR-TKI in advanced lung cancer patients." (PMID 32457635, 2020). "Studies on lung cancer cell lines and transgenic mice harboring EGFR mutations have shown the oncogenic potential of these mutations, with enhanced response to EGFR inhibitors." (PMID 32397295, 2020). "Using radiomic features, individual combinations of the seven selection features and four classification methods showed different EGFR diagnostic performances (AUC) for lung cancer BM." (PMID 32483122, 2020). "EGFR mutations in lung cancer were first detected in 2004 and have subsequently been widely examined, resulting in the development of new therapeutic strategies for patients with NSCLC." (PMID 32337844, 2020). "Due to the high incidence of EGFR mutation‐positive lung cancers, further investigation into available treatment options is crucial." (PMID 32495514, 2020). "In this study, we aimed to examine minimally invasive bronchial washing (BW)-derived extracellular vesicles (EVs) for EGFR mutation analysis in patients with lung cancer." (PMID 33007940, 2020).
lung cancer (continued). "A study looking at EGFR mutations in the CSF of lung cancer patients with CNS metastases showed that sequencing hotspots was more sensitive than sequencing all EGFR exons." (PMID 32133357, 2020). "In EGFR-mutated lung cancer, inhibitors of EGFR showed limited effectiveness because of specific site mutations." (PMID 32863957, 2020). "Our findings highlight the inhibitory effect of RPE against the hallmarks of lung cancer cells including proliferation, migration, and invasion, which was associated with the inhibition of EGFR activation and subsequent c-Raf-MEK and PTEN-mTOR-Akt signaling." (PMID 33158043, 2020). "Osimertinib is the most promising treatment option for patients with epidermal growth factor receptor (EGFR) mutation‐positive non‐small cell lung cancer (NSCLC) with acquired T790M resistance." (PMID 32068351, 2020). "TMB was negatively associated with clinical outcomes in metastatic EGFR mutant lung cancer patients treated with EGFR-TKI." (PMID 33996530, 2020). "The clinical course of EGFR mutant lung cancer is significantly heterogeneous, and acquisition of EGFR T790M mutation is the most frequent reason for first- and second-generation EGFR-TKIs68." (PMID 33219256, 2020). "It is possible that RB1 loss in EGFR mutant lung cancer cells will yield a similar, synthetically lethal interaction with these inhibitors." (PMID 32292420, 2020). "These involve genes like MUC16 (CA125) whose levels relate to different stages of NSCLC, and PTK7 that is associated with lymph node metastasis as well as ALK and EGFR mutations in lung cancer." (PMID 33255394, 2020). "Previously, we developed an allele-specific loop-mediated isothermal amplification (AS-LAMP) assay for screening germline and somatic de novo T790M EGFR mutation in lung cancer patients." (PMID 33067539, 2020). "Plasma samples of 28 lung cancer patients and 20 cancer-free individuals are tested for the EGFR mutations by CRISPR-Cas12a system and ddPCR." (PMID 32093010, 2020). "Examples include treatment of EGFR-mutation–positive lung cancer with mutant-EGFR–targeted inhibitors, or elevation of AFP as an indicator of liver cancer." (PMID 32993581, 2020). "In this review we will discuss on current and possible future application of liquid biopsy in EGFR-driven NSCLC, defined as lung cancers harboring targetable mutation in EGFR genes." (PMID 36046387, 2020). "Deletion in the 19th exon of the EGFR is one of the major activation mutations found in lung cancer patients." (PMID 33092268, 2020). "PNA clamping is ultrasensitive for detecting EGFR gene mutation when compared to traditional way of direct sequencing in non‐small cell lung cancer patients." (PMID 32838227, 2020). "Recent studies have shown that lung cancer with increased YES1 was more responsive to Dasatinib, and increased expression of YES1 was reported to be one of the acquired resistant mechanisms to EGFR inhibitors in lung cancer with EGFR mutations." (PMID 32923394, 2020). "In AXL-high-expressing EGFR-mutated lung cancer cells, osimertinib exposure inhibits ERK phosphorylation and thereby decreases the expression of SPRY4 maintained by ERK-mediated MAPK signal." (PMID 32929081, 2020). "Recent case report is available that suggested that TAMs in lung cancer can be a predictor of a positive response to anti-PD-1 antibodies (nivolumab) in patents with EGFR-mutated lung cancer." (PMID 33194645, 2020). "In our study, we observed lower lung cancer risk among never-smokers and Asian women with higher parity, suggesting that higher parity is inversely associated with lung cancer risk by inhibiting EGFR activation or mutation." (PMID 32977782, 2020). "We also show that, in lung cancer patients harboring EGFR mutations, the divergent CEAIn and CEAPd pattern (CEAIn ≥ 5 ng/mL and CEAPd < 5 ng/mL) is associated with new metastasis." (PMID 32034239, 2020).
lung cancer (continued). "This test encompasses 51 EGFR clinically relevant mutations from exons 18 to 21 in human lung cancer FFPE material (according to the latest IASLC atlas of EGFR testing in lung cancer)." (PMID 32245434, 2020). "For example, initial treatment with the third-generation TKI, osimertinib has gained success in improving survival in EGFR-mutated lung cancer, possibly due to the suppression of tumors harboring hidden T790M mutation." (PMID 33370365, 2020). "There were several previous studies focused on the simultaneous occurrence of ALK rearrangements and EGFR mutations in unifocal lung cancer." (PMID 32375829, 2020). "Lung cancer is well established as a highly heterogeneous tumor that harbors various gene alterations including mutations in EGFR, KRAS, BRAF, PD-L1, and PIK3CA, as well as ALK rearrangement and HER2 amplification." (PMID 33411683, 2020). "The detection of epidermal growth factor receptor (EGFR) mutation, based on tissue biopsy samples, provides a valuable guideline for the prognosis and precision medicine in patients with lung cancer." (PMID 33007940, 2020). "Activating mutations in EGFR gene are observed frequently in non-small-cell lung carcinoma patients, and EGFR gene polymorphisms are associated with the risk of lung cancer." (PMID 32937815, 2020). "Previous studies have shown that polymorphisms in CYP1A1 and GSTM1 and EGFR contribute to the increased risk of females for lung cancer." (PMID 32344833, 2020). "In contrast to kinase domain mutations found in lung cancer, glioma-specific extracellular domain mutants are known to respond poorly to EGFR inhibitors." (PMID 33009951, 2020). "In lung cancer, patients with mutation of common driver genes (such as EGFR and ALK) can benefit from targeted therapy." (PMID 33537237, 2020). "In particular, over 20% of lung cancer patients carry EGFR mutations that produce a constitutive activation of the EGF receptor." (PMID 33297362, 2020). "Massively parallel sequencing of tumors or liquid biopsy samples from 24 468 patients with lung cancer identified a total of 547 cases (2.24%) with EGFR e20ins mutations." (PMID 32412152, 2020). "Despite these limitations, this is the first prospective study assessing the feasibility of utilizing ctDNA alone in detecting EGFR mutations in patients with suspected lung cancer that lack histologic diagnosis." (PMID 31991049, 2020). "Clinical studies have demonstrated that osimertinib monotherapy induces an approximately 60% response rate and a durable benefit in patients with lung cancers harboring the EGFR T790M mutation." (PMID 32404161, 2020). "Epidermal growth factor receptor (EGFR)-mutated lung cancer occurs in 15–20% of patients with adenocarcinoma and is most commonly associated with nonsmokers and those of Asian ethnicity." (PMID 32992872, 2020). "An EGFR‐21‐L858R missense mutation was identified, which is the first case of a common gene mutation associated with non‐small cell lung cancer being found in a BA lesion." (PMID 33063939, 2020). "Patients with lung cancer and BMs harboring EGFR mutations exhibit better responses to treatment as well as different clinical features." (PMID 32483122, 2020). "BIM deletion polymorphisms are common in Asian populations, with an incidence of 12‐16% in lung cancer patients with EGFR mutations." (PMID 32508032, 2020). "High-throughput sequencing has also indicated the causality between mutations or fusions of some kinases with cancers, the most famous examples of which are L858R and T790M EGFR mutations in lung cancer and BCR-ABL fusion genes in chronic myeloid leukemia." (PMID 32944406, 2020). "Here, we report a case of distal‐type BA carrying an EGFR exon 21 p.L858R mutation, which is commonly associated with non‐small cell lung cancers (NSCLCs)." (PMID 33063939, 2020).
lung cancer (continued). "Firstly, we detected an increase in RIP1 expression induced by IR, which appeared to require phosphorylation of EGFR, which contains mutations in exons 18–21 encoding the TK domain in lung cancer." (PMID 32605153, 2020). "It is well-documented that the most common EGFR mutations including exon 19 deletions and L858R mutations strongly predict the sensitivity of lung cancer patients to tyrosine kinase inhibitor treatments." (PMID 32937815, 2020). "Most EGFR gene mutations can be targeted for therapy and thus is considered the most common “actionable” mutation in lung cancer patients (Castellanos, Feld, & Horn, 2017)." (PMID 32757330, 2020). "For lung cancer, in particular, the most common mutations found are in the epidermal growth factor receptor (EGFR) gene and the K-Raf kinase gene family (KRAS)." (PMID 32082488, 2020). "All laboratories that examine lung cancer specimens are advised to test for mutations in a minimum of one set of genes, namely, epidermal growth factor receptor (EGFR), ALK, and ROS1." (PMID 33425389, 2020). "The three studies suggested that the incidence of driver gene mutations in NSCLC patient is high, and lung cancer driver genes, such as EGFR, ALK, and RET are risk factors for brain metastasis in advanced NSCLC patients." (PMID 33537237, 2020). "EGFR mutation in lung cancer cells, especially in the case of adenocarcinoma, is correlated with an increased tumor growth and cancer progression." (PMID 36046486, 2020). "A study using an EGFR-mutant lung cancer mouse model showed that the loss of Mig-6 accelerates the initiation and progression of mutant EGFR-driven lung adenocarcinoma." (PMID 32552717, 2020). "Here, we show that while AXL-low expressing EGFR mutated lung cancer (EGFRmut-LC) cells are more sensitive to osimertinib than AXL-high expressing EGFRmut-LC cells, a small population emerge osimertinib tolerance." (PMID 32929081, 2020). "After associating these EGFR activating mutations between primary lung cancer and NM, the present data shows that the EGFR activating mutations in the CSF samples were roughly consistent with those of primary lung cancer." (PMID 32711494, 2020). "EGFR s768i point mutation occurs in 1%–2% of EGFR mutant lung cancers, and can occur alone but often in combination with other EGFR sensitive mutations." (PMID 32776462, 2020). "The current gold standard for detecting EGFR mutation in lung cancer patients in the clinic is cell cytology using tissue biopsy samples." (PMID 33007940, 2020). "Research has predominantly focused on EGFR mutation for lung cancer-related drug development, and there are many EGFR antagonists that have been used for clinical treatment." (PMID 33060649, 2020). "The assessment of the EGFR gene mutation status in lung cancer tissues has important predictive value for the efficacy of EGFR‐TKI." (PMID 31691525, 2020). "The emergence of EGFR-TKIs has led to an astounding improvement in survival of patients with EGFR-mutated lung cancer." (PMID 33138052, 2020). "In various studies, Sanger sequencing has correlated familial clustering of lung cancer with a germline T790M mutation in EGFR." (PMID 32104210, 2020). "Several clinical trials have been performed to evaluate the efficacy and safety of treatments for lung cancer patients with EGFR mutations." (PMID 32107398, 2020). "We revealed that FAM83A knockdown–induced inhibition of lung cancer cell growth and motility was partially caused by the suppression of EGFR/MAPK/CHKA signaling activity." (PMID 33266425, 2020). "Considering these issues, we chose the transient combination of the IGF-1R inhibitor with osimertinib, demonstrating a favorable efficacy and safety in the CDXs and PDX models of AXL-low-expressing EGFR-mutated lung cancer." (PMID 32929081, 2020).